Y_RNA (Y RNA )
Gene: Miscellaneous RNA gene on chromosome X (16,912,215 to 16,912,317, reverse strand). Ensembl gene ENSG00000199410.
Homologues: Orthologues: chimpanzee Y_RNA (99% identical), guinea pig Y_RNA (86% identical). Paralogues in human: Y_RNA (86% identical), RNY3 (85% identical), Y_RNA (85% identical), Y_RNA (84% identical), Y_RNA (83% identical), RNY3P1 (83% identical), RNY3P16 (82% identical), RNY3P2 (82% identical), RNY3P9 (82% identical), Y_RNA (82% identical), RNY3P11 (81% identical), RNY3P14 (81% identical), and 92 more.